PRODH (proline dehydrogenase 1)
Diseases named in the same sentence as PRODH in open-access papers (continued):
Sharing a sentence is not in itself a finding about the gene and the disease.
osteosarcoma (1 paper, 2024). A usually aggressive malignant bone-forming mesenchymal neoplasm, predominantly affecting adolescents and young adults. "Interestingly, PRODH in a human osteosarcoma cell line (U2OS) induced cell senescence associated with the increase in ROS production and accumulation of DNA damage, a finding that is in stark contrast to our current finding with naive hESCs." (PMID 38480845, 2024).
ovarian carcinoma (1 paper, 2024). A malignant neoplasm originating from the surface ovarian epithelium. "Secondly, the risk of ovarian cancer increased with age in association with MMP3, MMP10, MMP7, TIMP3, POX/PRODH, PYCR1, PYCR3 to indicate degenerative histological changes." (PMID 38397798, 2024).
renal cell carcinoma (1 paper, 2024). "Importantly, miR-23b downregulates POX/PRODH in renal cell carcinoma." (PMID 38544804, 2024).
rhabdomyosarcoma (1 paper, 2013). A rare aggressive malignant mesenchymal neoplasm arising from skeletal muscle. "The rhabdomyosarcoma-derived Rh30 cell line was also investigated for PRODH expression." (PMID 23861960, 2013).
squamous cell carcinoma (1 paper, 2020). A carcinoma arising from squamous epithelial cells. "The results of the Western immunoblot test performed on tissue material revealed significant differences in the expression of selected proteins involved in apoptosis-related proline metabolism (PRODH/POX, PPARγ, HIF-1α) between squamous cell carcinoma and normal mucosa." (PMID 31935820, 2020).
stomach cancer (1 paper, 2013). "The present study demonstrated the upregulation of PRODH mRNA expression and superoxide generation in the gastric cancer cell line MKN45 following 5-FU treatment." (PMID 23232983, 2013). "Although PRODH expression levels were found to be much lower in several types of cancers, including stomach cancer, as compared to normal tissues, the relationship between PRODH and the anticancer effect of 5-FU has yet to be elucidated." (PMID 23232983, 2013).
teratocarcinoma (1 paper, 2019). A germ cell tumor characterized by the presence of an embryonal carcinoma component and a teratoma component. "In contrast, another study in a different teratocarcinoma, Tera-1, found that a HERV LTR co-opted to regulate the PRODH gene exhibited an enhancer effect in responsive to Sox2 and not NF-κB, suggesting that NF-κB activation alone might not greatly alter HERV expression." (PMID 31333597, 2019).
tongue squamous cell carcinoma (1 paper, 2021). A squamous cell carcinoma that arises from the tongue.
tumor (73 papers, 2012 to 2025). "In some stress situations (metabolic, oxygen and glucose deficiency, inflammation, genotoxicity) PRODH/POX activation support tumour growth." (PMID 29568391, 2018). "In addition, PRODH has also been associated with cognition, and it is a putative tumor suppressor." (PMID 37564635, 2023). "In our study, we observed a consistent downregulation of PRODH in the liver tissues of silver carp subjected to hypoxic stress, which contrasts with observations made in tumor hypoxic microenvironments." (PMID 41463861, 2025). "GBM cells that have infiltrated normal brain show increased gene expression of PRODH compared to tumour cells derived from the core, calling for further study into the role of proline in tumour metabolism." (PMID 39816516, 2025). "In future studies, we will testify the relationship between PRODH, ferroptosis, and tamoxifen response using mouse models and patient tumor tissues." (PMID 39457440, 2024). "It has been shown that PRODH-dependent ATP production promotes tumor cell survival in energy stress, while PRODH-dependent ROS production induces cancer cell apoptosis and functions as a tumor suppressor." (PMID 39457440, 2024). "As a result, fer-1 treatment reversed the effect of PRODH on tumor growth under tamoxifen treatment." (PMID 39457440, 2024). "In the studied brain–tumor pairs, POX/PRODH in GG4 is significantly suppressed, with unequivocal inter-modality agreement." (PMID 38275897, 2024). "High POX/PRODH activity can be considered as a tumor survival factor through ATP production or ROS-induced autophagy." (PMID 38397798, 2024). "Several NSAIDs, including Ibuprofen, Indomethacin, Diclofenac, Sulforaphane, and Zaltoprofen, have been found to induce apoptosis in tumor cells by upregulating PRODH/POX expression and increasing ROS production." (PMID 39598398, 2024). "PRODH was observed as granular immunoreactive deposits in the cytoplasm of tumor cells, with the intensity and percentage of immunoreactive cells variable from case to case." (PMID 38255788, 2024). "The results confirm changes in proline metabolism in GG4, with a low-POX/PRODH/high-PYCR pattern like that in other neoplasms." (PMID 38275897, 2024). "In comparison to the control brain tissue, expression of POX/PRODH mRNA was 68% lower in tumor tissue (p = 0.0002)." (PMID 38275897, 2024). "The study revealed that COMT was expressed at high levels in all cell lines of GBMLGG patients, HTR2A showed more overexpression in tumor cells, and PRODH exhibited more overexpression in T cells." (PMID 37564635, 2023). "Over a decade ago, Liu and his colleagues discovered that PRODH significantly reduced tumor formation by inducing cell cycle arrest in the G2 phase, potentially through the mediation of the GADD (growth arrest and DNA damage inducible gene) family." (PMID 38023181, 2023). "PRODH had elevated expression in 4 tumor types (GBMLGG, LGG, SKCM, and SKCM-M) with poor prognosis and low expression in 6 tumors (CESC, LUAD, KIRP, PRAD, KIRC, and LUSC)." (PMID 37564635, 2023). "Based on current research, it is evident that proline catabolism and PRODH are important parts of the tumor process." (PMID 38023181, 2023). "On one hand, the ability of PRODH to induce apoptosis and senescence in cancer cells reflects its role as a tumor suppressor." (PMID 38023181, 2023). "The role of proline production and catabolism in cancer is complex and appears to be tissue dependent, with studies showing both tumor-supportive and tumor-suppressive roles for enzymes such as PRODH." (PMID 37672588, 2023). "Since PRODH/POX is considered as an inhibitory factor in tumor progression, the metabolism of its substrate, proline, in neoplastic cells is of great importance." (PMID 35733940, 2022).
tumor (continued). "In vivo study showed that overexpressed PRODH/POX favors inhibition of tumor growth suggesting the strongly pronounced generation of P5C, as an intermediate for the TCA cycle metabolites, and ROS." (PMID 34451829, 2021). "In view of the inhibitory role of PRODH/POX in tumor progression, all those metabolic cycles are of great importance in the PRODH/POX-dependent functions in neoplastic cells." (PMID 33818628, 2021). "It has been discovered that PRODH/POX is a tumor suppressor and, by ROS signaling, initiates apoptosis, limits tumor cell growth, and arrests the cell cycle progression." (PMID 34577574, 2021). "In view of the inhibitory role of PRODH/POX in tumor progression, the metabolism of proline in neoplastic cells is therefore of great importance." (PMID 34944532, 2021). "Functionally, PRODH activity drives cell proliferation and tumor growth in vivo and promotes cell migration and invasion." (PMID 33083024, 2020). "The combination of CBIO and l-tetrahydro-2-furoic acid (THFA), a specific inhibitor for PRODH, had a more marked effect on inhibiting senescence than the single treatment with either inhibitor alone in both tumor U2OS and normal Hs68 cells." (PMID 30659069, 2019). "We confirmed these findings in vivo, which revealed changed proline dehydrogenase (PRODH) expression in tumor tissues, which in turn influences tumor growth and T cell infiltration." (PMID 30545412, 2018). "We also verified our findings in animal model, where PRODH over-expression enhanced tumor growth and decreased T cells infiltration in tumors, and PRODH knockdown showed opposite phenomenon." (PMID 30545412, 2018). "Elegant studies (cited in this paper) of James Phang’s group documented PRODH/POX as a mitochondrial tumor suppressor." (PMID 29568391, 2018). "During hypoxia, tumor cells respond with either PRODH/POX-mediated ATP generation under conditions of low glucose, or pro-survival, ROS-mediated autophagy induction when glucose levels were normal." (PMID 26660760, 2016). "Superoxide generated by PRODH makes cells more sensitive to stress, probably explaining the pro-apoptotic and tumor suppressor function of PRODH." (PMID 23024808, 2012). "Additionally, studies have demonstrated that PRODH expression is upregulated in tumor hypoxic environments, promoting cellular autophagy through AMPK activation to enhance cell survival under low oxygen conditions." (PMID 41463861, 2025). "Whether the induction of full-blown senescence can be obtained by sole PRODH expression or whether PRODH-induced senescence may represent a tumor-suppressive mechanism needs further evaluation." (PMID 38255788, 2024). "PRODH is critical for proline degradation and is a tumor suppressor in many types of cancers." (PMID 39457440, 2024). "Moreover, PRODH significantly impacts cancer progression through its dual role in ATP production and ROS generation, acting as both a tumor suppressor and oncogene, making it a critical therapeutic target for HCC." (PMID 38693536, 2024). "However, in other types of cancers such as lung and pancreas cancer, PRODH is up-regulated and functions as a tumor promoter." (PMID 39457440, 2024). "A Xenograft tumor assay was used to detect the role of PRODH in tumor growth." (PMID 39457440, 2024). "Therefore, this study shows the possibility of slowing PDAC tumor growth and reducing tumor survival by specifically targeting proline metabolism through PRODH inhibition." (PMID 38023181, 2023).
tumor (continued). "Notably, the role of PRODH in cancer is still complicated and unclear, and primarily depends on the cancer type and tumor microenvironment." (PMID 38023181, 2023). "Additionally, the researchers demonstrated that the expression of POX/PRODH promotes tumor growth in vivo and in vitro." (PMID 35454935, 2022). "PRODH has been involved in NSCLC metastasis as shown, both in vitro and in vivo, and ADORA1, which is highly expressed in EGFR-mutant NSCLC biopsies, has been associated involved in tumor-immune evasion in NSCLC xenograft models." (PMID 36551790, 2022). "Therefore, PRODH/POX is considered as a tumor suppressor or pro-survival factor, depending on the environmental conditions." (PMID 33818628, 2021). "Taken together, PRODH/POX has distinct functions depending on the tumor microenvironment." (PMID 34577574, 2021). "The inhibitory role of PRODH/POX in tumor progression is well established." (PMID 34944532, 2021). "PRODH/POX indirectly inhibits the process of angiogenesis in tumor tissues and thus tumor growth." (PMID 34943229, 2021). "ProDH is a recognized source of ROS production, mediating mitochondrial apoptosis and tumor growth." (PMID 34603395, 2021). "In addition, to induce apoptotic cell death, PRODH/POX inhibits tumor progression by down-regulating growth and differentiation of tumor cells, by inhibiting the cell cycle at the G2-M checkpoint." (PMID 34769188, 2021). "Hypoxia and nutrient depletion are important characteristics of the tumor microenvironment, where PRODH may serve as a tumor survival factor." (PMID 32511103, 2020). "Indeed, PRODH supports tumor metastasis formation, and inhibiting its activity impairs cancer cell growth, indicating PRODH is a potential drug target." (PMID 32511103, 2020). "The upregulation of PRODH increased tumor growth, and PRODH knockdown reversed it." (PMID 30545412, 2018). "Strikingly, the changes in PRODH expression influenced tumor growth in animal model." (PMID 30545412, 2018). "Expression of PRODH (proline dehydrogenase), a putative tumor suppressor, was lower in GBM." (PMID 28245795, 2017). "Importantly, lower POX/PRODH activity may support tumor growth through a mechanism involving less-pronounced anti-tumor properties." (PMID 38275897, 2024). "Furthermore, this study conducted a xenograft model to validate their in vitro findings and found that upregulation of PRODH in animal models contributes to tumor growth and decreased T-cell infiltration, while PRODH knockdown accelerates CD3+, CD4+, and CD8+ T cells infiltration." (PMID 38023181, 2023). "On the one hand, POX/PRODH might act as a tumor survival factor through AMPK kinase or peroxisome proliferator-activated receptors-γ (PPARγ) when induced under stress conditions, e.g., in nutrient or oxygen deprivation or stimulation by oxidized lipids (oxLDL)." (PMID 35454935, 2022). "An additional study demonstrated that ProDH/Pox may promote tumor metastasis." (PMID 33477430, 2021). "Because tumor mutational burden (TMB) serves as a biomarker to select patients who might benefit from immune checkpoint inhibitors, we also evaluated association between TMB and cg14326354PRODH as well as PRODH expression." (PMID 32511103, 2020).
tumor (continued). "Moreover, in the tumor samples analyzed, we observed that PRODH expression diminished with increasing stage or grading of the ADC samples, suggesting that the function of PRODH in these cancer cells may be related to the maintenance of differentiation and cellular homeostasis." (PMID 38255788, 2024). "We also found a perfect correlation between PRODH transcript and protein levels, both in tumor tissues analyzed by immunohistochemistry and in lung ADC cell lines, suggesting that PRODH is mainly regulated at the transcriptional level." (PMID 38255788, 2024). "We noticed the activation of the proline cycle (↑ PEPD, POX/PRODH and PYCR1) to indicate constant remodeling (synthesis and degradation) of matrix collagen, which in turn can contribute to tumor heterogeneity." (PMID 38397798, 2024). "Both low and high proliferative luminal tumours showed weak positive correlation between GLS2 protein and ALDH18A1 (p < 0.001), ALDH4A1 (p < 0.01), ATF4 (p = 0.001), PRODH (p < 0.001), SLC38A2 (p ≤ 0.001) and SLC7A11 (p < 0.001)." (PMID 34439127, 2021). "Overexpression of miR-23b* attenuated PRODH/POX activity, ROS generation, apoptosis and augmented HIF-1 signalling contributing to oncogenesis and tumor progression." (PMID 33818628, 2021). "The least distinct differences in POX, PPARγ and HIF1-α expression were found in the group of highly differentiated tumours (G1, KI-67 < 40%)—The average expression of PRODH/POX and PPARγ was 88% compared to normal tissue, while HIF1α was 130%." (PMID 31935820, 2020). "The most significant differences in the expression of selected proteins were observed in the group of poorly differentiated tumours (G3, KI-67 > 70%): the mean value of PRODH/POX expression was 52% compared to normal tissue, 48% of PPARγ, and 163% of HIF-1α." (PMID 31935820, 2020). "PRODH/POX can generate ROS and function as a tumor suppressor gene; the progression of tumors requires that the suppressor activity of PRODH be downregulated." (PMID 28990419, 2019). "Proline oxidase (POX; also named as proline dehydrogenase; PRODH), the first step in proline catabolism, is a mitochondrial inner membrane enzyme and a tumor suppressor that impedes proliferation and induces apoptosis." (PMID 26690121, 2015). "Additionally, our study demonstrated that deferasirox, an oral iron chelator, significantly diminishes cell viability and tumor growth in KRAS-mutant PDAC by targeting FTH1-mediated pathways and altering the PYCR1/PRODH expression ratio." (PMID 39294443, 2024). "Moreover, inhibition of Proline dehydrogenase 1 (PRODH1) using deshydroproline reduced proline utilization by PDAC cells, minimizing tumor size, cell growth, and viability in laboratory experiments." (PMID 39199647, 2024). "Likewise, proline dehydrogenase (oxidase) (PRODH/POX), which catalyzes proline to P5C, functions as a tumor suppressor." (PMID 36937389, 2023). "Although its role in NSPC development has not been previously examined, PRODH has been extensively investigated in other highly proliferative cells, such as cancer cells where it can act as either a tumor suppressor or oncogene depending on context." (PMID 37794116, 2023). "PRODH promotes NSCLC tumorigenesis and could promote the expression of inflammatory genes and tumor cell proliferation." (PMID 36295809, 2022). "What is the common denominator for PRODH and P5CS in the context of tumor growth and progression?" (PMID 34825974, 2021). "Compared with corresponding non-neoplastic tissue, the expression of PRODH was up-regulated in all of the tumor tissues." (PMID 30545412, 2018). "It was suggested that PRODH/POX-dependent down-regulation of HIF-1 signalling may affect cell cancer invasion, tumour growth and angiogenesis." (PMID 29568391, 2018).
tumor (continued). "Increased expression of POX/PRODH exerted a reciprocal inhibitory effect on the expression of the cyclooxygenase-2 (COX-2) enzyme, counteracting the prostaglandin-driven development of an inflammatory tumor milieu known for worsening the prognosis of several malignancies." (PMID 35454935, 2022). "Three independent prognostic DEOSGs (PRODH, STK24, and MAP1LC3A) were identified by multivariate Cox proportional hazards regression analysis after consideration of confounding factors such as gender, tumor, node, and metastasis (TNM) stage, tumor (T) stage, and node (N) stage." (PMID 36180848, 2022).